MTOR (mechanistic target of rapamycin kinase)
Diseases named in the same sentence as MTOR in open-access papers (continued):
Sharing a sentence is not in itself a finding about the gene and the disease.
lung cancer (continued). "For example, UCA1 can induce acquired resistance to EGFR-tyrosine kinase inhibitors (TKIs) in EGFR-mutant nonsmall cell lung cancer by activating the AKT/mTOR pathway." (PMID 30377411, 2018). "The results suggest that the expression of PGAM1 is mTOR dependent in rodent cells and human lung cancer." (PMID 29362480, 2018). "Work performed in lung carcinoma has shown the ability of extracts from cigarette smoke to drive activators of the mTOR pathway." (PMID 30308005, 2018). "This study was aimed at bringing further insight into general mechanisms of AQR in the context of the application of PI3K/mTOR inhibitors to EGFR inhibitor-refractory lung cancer." (PMID 29299135, 2017). "We determined that inhibition of AKT activation resulted in downregulation of pmTOR (ser2448) expression in lung cancer cells, showing inhibition of mTOR activation in H460 and A549 cells." (PMID 29234489, 2017). "The PI3K/AKT/mTOR signal‐transduction pathway plays a significant role in the progression of human lung cancer." (PMID 28444871, 2017). "Increasing evidence suggested that alterations of phosphatidylinositol-3-kinases (PI3K)/Akt/mTOR pathway were identified and involved in the pathogenesis of lung cancer for therapeutic strategy." (PMID 28903328, 2017). "Our results demonstrated that glipizidesensitizes human lung cancer cells to TRAIL-mediated apoptosis via Akt/mTOR/autophagy pathways." (PMID 29245957, 2017). "According to present knowledge, PI3K/AKT/mTOR is a crucial signaling pathway in tumorigenesis, including human lung cancer." (PMID 29296237, 2017). "Our study suggests a pathway differs from mTOR cascade in that EGFRhigh lung cancer cells survive Met with sustained phosphorylation of EGFR in response to EGF, and increased sensitivity to Erlo, one of the most wildly used EGFR-TKIs at present in the clinic." (PMID 29312591, 2017). "Further, knockdown of AMPK α-subunit, i) blocked metformin- and RT induction of p21cip1, ii) allowed activation of Akt and mTOR and iii) blocked the inhibition of lung cancer cell proliferation mediated by metformin and RT." (PMID 28915708, 2017). "Meanwhile, cordycepin stimulated autophagy through suppressing mTOR signaling pathway in lung cancer cells." (PMID 28035061, 2017). "Piplartine was shown to reduce the number of viable cells and induces cell apoptosis on HCT116 cells by JNK signaling pathway, and induces apoptosis and autophagy through modulation of the PI3K/Akt/mTOR pathway in human lung cancer cells." (PMID 29262647, 2017). "Among the 20 pathways, PI3K-Akt signaling pathway, Wnt signaling pathway and mTOR signaling pathway have been confirmed to be correlated with multidrug resistance, since treatment failure of lung cancer is partly related to these pathways." (PMID 28178672, 2017). "To further explore the relationship between PD-L1 and mTOR activity in lung cancer cells, we treated three NSCLC cell lines in which PD-L1 is highly expressed—H157, H1975, and HCC827 —with rapamycin for 24 hours." (PMID 29296193, 2017). "In our study, the expression levels of p-AKT and p-mTOR were down-regulated in lung cancer cells transfected with si-BCAP or miR-486 mimic." (PMID 28924214, 2017). "In the present study, VJ, a small molecule, simultaneously inhibited EGFR, AKT, mTOR activation, and effectively suppressed cell proliferation and promoted induction of apoptosis in lung cancer cells, expressing wild-type EGFR." (PMID 29234489, 2017). "c-Met gene overexpression analysis further demonstrated that curcumin suppressed lung cancer cell EMT by inhibiting c-Met/Akt/mTOR signaling pathways." (PMID 27525306, 2016).
lung cancer (continued). "Our results revealed that auranofin inhibit PI3K/AKT/mTOR axis and induce potent anticancer activity in a subset of lung cancer cell lines." (PMID 26657290, 2016). "In the present study, we found miR-206-MET axis regualted PI3K/AKT/mTOR pathway in lung cancer cells." (PMID 27014910, 2016). "The PI3K/AKT/mTOR signaling pathway is well-known to play essential roles in cell proliferation, invasion, apoptosis, and angiogenesis in lung cancer." (PMID 27980454, 2016). "Both Akt-mTOR and Erk signaling cascades are important for lung cancer cell survival and/or apoptosis resistance." (PMID 27626799, 2016). "To further dissect the underlying molecular mechanism of compound 5i induced autophagy, we detected the activity of PI3K/AKT/mTOR pathway in H460, A549, and H1975 lung cancer cells upon 5i treatment." (PMID 27786281, 2016). "PI3K-Akt-mTOR signaling is indispensable for the EGFR-mediated regulation of aerobic glycolysis in lung cancer cells." (PMID 26918353, 2016). "Taken together, miR-206 inhibits HGF-induced EMT and angiogenesis in lung cancer by suppressing c-Met/PI3k/Akt/mTOR signaling." (PMID 26919096, 2016). "Elevated ASCT2 expression promoted cell growth and survival in colorectal cancer and lung cancer, partially mediated by mammalian target of rapamycin (mTOR) signaling." (PMID 28036362, 2016). "miR-143, downregulated by mTOR activation, regulates cancer glycolysis and inhibits cancer cell proliferation and tumor formation via targeting HK II in human lung cancer." (PMID 26918353, 2016). "Forced expression of miR-208a promoted cell proliferation and induced radioresistance via targeting p21 with a corresponding activation of the AKT/mTOR pathway in lung cancer cells, whereas down-regulation of miR-208a resulted in the opposite effects." (PMID 26754670, 2016). "More importantly, curcumin suppresses HGF-induced phosphorylation of c-Met/Akt/mTOR in human lung cancer cells." (PMID 27525306, 2016). "It has been reported that HGF/c-Met signaling is important in EMT and metastasis and its downstream PI3k/Akt/mTOR signaling is one of the major pathways activated in cancer cells, including lung cancer cells." (PMID 26919096, 2016). "Our finding that NTRK2 activates PI3K/mTOR signaling is consistent with recent studies that NTRK2 promotes lung cancer and chondrosarcoma survival and metastasis by activating PI3K/AKT signaling." (PMID 27672444, 2016). "It is clear that when cultured on human fibroblast-derived ECM, lung cancer cell lines have less activated MAPK activation as well as decreased mTOR and cell cycle regulating pathways." (PMID 26371754, 2015). "As an example, the suppression of mTOR activity and the decrease of mTOR phosphorylation have been observed in lung cancer H1299 cells after Twist1 knockdown." (PMID 26360779, 2015). "Enhanced apoptosis and tumor growth suppression by combination of MEK and mTOR inhibitors was previously observed in HRAS wild-type lung cancer cell lines." (PMID 26544513, 2015). "MicroRNA-193a-3p and −5p function as tumour suppressors and inhibit the metastasis of lung cancer by down-regulating the ERBB4/PIK3R3/mTOR/S6K2 signalling pathway." (PMID 26395400, 2015). "We conclude that autophagy plays a pro-death role in acquired MDR and upregulation of autophagy by GMI via Akt/mTOR inhibition provides a potential strategy for overcoming MDR in the treatment of lung cancers." (PMID 25946033, 2015). "Combinations of MEK and mTOR inhibitors have been tested in several carcinomas, including lung cancer, melanoma, colorectal cancer, and pancreatic cancer, but their combined effect on sarcomas have only been reported for rhabdomysarcoma." (PMID 25955301, 2015). "Recent studies have shown that aberrant activation of mTOR is involved in many cancers, including ovarian carcinoma, lung cancer, prostate cancer and mantle cell lymphoma." (PMID 25333576, 2015).
lung cancer (continued). "Compared with tumor cells transfected with siScr, Since aberrant excessive activation of COX-2/PGE2 and AKT/mTOR pathways are crucial for tumor cell growth survival, and invasion in lung cancers." (PMID 25605013, 2015). "A growing body of evidences is supporting the PI3K-Akt-mTOR axis as a potent therapy target in several types of cancers including lung cancer." (PMID 26036632, 2015). "Gal-1 has been reported to promote stem cells proliferation by up-regulating AKT/mTOR pathway, or promote lung cancer progression and chemoresistence by upregulating COX-2/PGE2 pathway." (PMID 25605013, 2015). "More promising results have been observed in lung cancer and renal cell carcinoma models if the mTOR-pathway is targeted by inhibiting both AKT and mTOR." (PMID 25945839, 2015). "The dysregulation of Akt/mTOR pathway was reported to contribute to lung cancer development and maintenance." (PMID 25605013, 2015). "Our analysis also revealed that SYK023 decreased the phosphorylation of Src, FAK, Akt and mTOR, all of which are involved in cell survival, apoptotic pathways, and actin polymerization in lung cancer." (PMID 25909174, 2015). "The MEK inhibitor AZD6244 and the dual PI3K/mTOR inhibitor NVP-BEZ235 were tested in glioblastoma and lung carcinoma cells, which differ in their mutational status in the MAPK and the PI3K/mTOR pathways." (PMID 26498922, 2015). "The PI3K/Akt/mTOR signaling pathway is involved in tumorigenesis, translation of proteins for cell cycle progression, and lung cancer cell proliferation." (PMID 24989178, 2014). "Radiation-induced activation of the PI3K/Akt/mTOR signaling pathway increases VEGF-C expression in lung cancer cells, thereby promoting endothelial cell proliferation." (PMID 24989178, 2014). "The PI3K/Akt/mTOR is an important intracellular signaling pathway in cell apoptosis, and this deregulated cascade is reported to contribute to lung cancer development and maintenance." (PMID 24884778, 2014). "Results from preclinical studies have indicated that factors antagonizing the mTOR pathway exert an antitumor effect on lung cancer." (PMID 25360163, 2014). "Our findings confirm the inhibitory role of the tuberous sclerosis complex for mTOR activation in lung cancer cell lines." (PMID 24593867, 2014). "Preliminary results indicate IL-24 effectively inhibits Akt1/2 and its downstream target mTOR in lung cancer cells resulting in inhibition of cell growth, cell migration and invasion." (PMID 24377906, 2013). "Our results further suggest that the Src-Akt-mTOR axis, a group of promising therapeutic targets in lung cancer, acts as a signal transducer of the fibrotic tumor microenvironment." (PMID 23409704, 2013). "In the present study, we demonstrated that mTOR inhibitors suppressed the growth of EGFR mutant lung cancer cells, even in the presence of HGF, in vitro and in vivo." (PMID 23690929, 2013). "Our current study is preclinical, and we demonstrated that mTOR inhibitors showed considerable efficacy in lung cancer cells with HGF-mediated resistance to EGFR-TKI resistance both in vitro and in vivo." (PMID 23690929, 2013). "In continuation with these reports our laboratory has pursued to dissect the PI3K/Akt/mTOR pathway in human lung cancer cells that have been stably transfected to express exogenous IL-24." (PMID 24377906, 2013). "Upregulation of autophagy by inhibitors of caspase-3 and mTOR enhanced radiotherapy responses in a mouse model of lung cancer." (PMID 23760551, 2013). "The results show that RV treatment significant inhibits the expression levels of p-Akt and p-mTOR in irradiated H460 lung cancer cells." (PMID 24141489, 2013). "Our results also suggest that mTOR inhibitors have advantage of several mechanisms to suppress the growth of EGFR-TKI resistance triggered by HGF in EGFR mutant lung cancer cells." (PMID 23690929, 2013).
lung cancer (continued). "More recent studies conducted in our laboratory has revealed IL-24 when expressed at pharmacological levels in human H1299 lung cancer cells inhibited the Akt/mTOR signaling pathway resulting in suppression of the tumor cell migratory function." (PMID 24377906, 2013). "The present study demonstrated that fucoidan effectively down regulates the expression of MMP-2 through the inhibitions of PI3K-Akt-mTOR as well as ERK1/2 signaling pathways in A549 human lung cancer cells." (PMID 23226337, 2012). "In conclusion, it is the first time that fucoidan is revealed to inhibit MMP-2 activity via the suppression of PI3K-Akt-mTOR and NF-kB signaling pathway in A549 lung cancer cells, resulting in the down regulation of cancer cell migration and invasion." (PMID 23226337, 2012). "Numerous downstream molecular pathways, such as EGF/RAS/RAF/MEK/ERK and PI3K/AKT/mTOR are identified as having a key role in the pathogenesis of various forms of human cancer, including lung cancer." (PMID 24281308, 2012). "In EGFR mutant lung cancer cells, inhibition of PI3K/mTOR and MEK were directly linked to MCL-1 downregulation and BIM upregulation, respectively." (PMID 22808163, 2012). "These preclinical results support suppression of both the MEK and mTOR pathways in lung cancer therapy and indicate that both pathways converge to regulate the initiation of protein translation." (PMID 23085539, 2012). "Treatment of inducible murine lung cancers containing KRAS and PIK3CA mutations with PI3K/mTOR (NVP-BEZ235) and MEK (selumetinib) inhibitors led to an enhanced response." (PMID 23085539, 2012). "Irradiated xenografts of the two lung cancer types showed reduced levels of phosphorylation of 4EBP1 (P-4EBP1) indicating reduced mTOR activity (reduction by 81.0 ± 4.75% and 47.0 ± 3.20% in A549 and H1299 xenografts, respectively)." (PMID 22607554, 2012). "Here we compare the effects of C75 and EGCG on lipogenesis (FASN activity), fatty acid oxidation (CPT activity), cellular proliferation, induction of apoptosis and cell signaling (EGFR, ERK1/2, AKT and mTOR) in A549 lung carcinoma cells." (PMID 22769244, 2012). "We evaluated in vitro the effects of C75 and EGCG on fatty acid metabolism (FASN and CPT enzymes), cellular proliferation, apoptosis and cell signaling (EGFR, ERK1/2, AKT and mTOR) in human A549 lung carcinoma cells." (PMID 22769244, 2012). "Activation of PI3K-Akt-mTOR pathway has been detected in many types of tumors including lung cancer, which is considered to be important for the survival, proliferation, angiogenesis and resistance of cancer cells to chemotherapy." (PMID 21392382, 2011). "In conclusion, the present study demonstrates that mTOR inhibition by rapamycin suppresses lung cancer cell growth and sensitizes tumor cells to docetaxel-induced cytotoxicity." (PMID 21392382, 2011). "Recent reports have suggested that PI3K/Akt/mTOR pathway is often activated in various forms of lung cancer and that this pathway is considered to be important for cancer cells' survival, proliferation, angiogenesis and resistance to chemotherapy." (PMID 21392382, 2011). "The clinical experience with analogues of rapamycin that have been tested as cancer therapeutics is consistent with these preclinical observations, in that mTOR inhibitors only have modest activity as single agents in patients with advanced lung cancer." (PMID 19330036, 2009). "Inhibitors of mTOR have already been investigated in lung cancer, with clear evidence of anticancer activity both as single agents and in combination with cytotoxic chemotherapy and radiation." (PMID 18728656, 2008). "These Rapamycin analogs are direct inhibitors of the prolyl isomerase FKBP12, which then inhibits mTOR, and are in clinical trials in kidney, breast and lung cancer." (PMID 19077306, 2008).
lung cancer (continued). "The efficacy of mTOR-targeted therapy in this benign tumour of the lung, marked by one aspect of mTOR activation, certainly is of interest due to its parallel biology in lung cancer." (PMID 18728656, 2008). "However, during lung cancer progression, aberrant activation of the mTOR pathway strongly promotes tumor malignancy." (PMID 40510156, 2025). "Furthermore, LIQ suppressed levels of PI3K, Akt, and mTOR in lung cancer cells, suggesting that this compound induced anti-tumor activities by the inhibition of PI3K/Akt/mTOR signaling pathways." (PMID 40723212, 2025). "Although there have been few studies on the PI3K/AKT/mTOR pathway in canine PC, the results of this study may contribute to the establishment of novel therapies for canine PC and human lung cancer research." (PMID 40563640, 2025). "Furthermore, our findings indicate that SM-3 induces autophagy in lung cancer cells and suppresses self-renewal in spheroids and organoids formation by inhibiting the mTOR pathway." (PMID 40287470, 2025). "Importantly, we found that the efficacy of mTOR inhibitors in treating lung cancer was significantly enhanced in a mouse xenograft model when Ephexin1 was deficient." (PMID 40855114, 2025). "In conclusion, the current results showed that Rosa synergistically improves the chemotherapeutic potential of cisplatin in lung cancer cells by suppressing the TLR2/MyD88/ TRAF6/NF-κB signal pathway together with the PI3K/AKT/mTOR and Gal-1 which consequently, inhibits proliferation." (PMID 40022036, 2025). "Additionally, SM-3 treatment resulted in decreased expression of stem cell markers (CD133, CD44, and ALDH1A1) and transcription factors (OCT4, NANOG, and SOX2) in spheroids and organoids from human lung cancer cells by inhibiting the mTOR/pAkt pathway." (PMID 40287470, 2025). "mTOR-driven aberrant suppression of autophagy sensitizes cisplatin-resistant lung cancer to 2-DG." (PMID 39814550, 2025). "The current study demonstrated that the AKT inhibitor MK2206 or the mTOR inhibitor rapamycin could mitigate the stemness of gefitinib-resistant lung cancer cells and enhance their sensitivity to gefitinib by suppressing the mTOR signaling pathway." (PMID 39744423, 2025). "Further studies on mTOR inhibitors in canine PC may lead to personalized medicine for canine PC and serve as a useful model for research on human lung cancer." (PMID 40563640, 2025). "Cell line sensitivity data suggests that alternative clinical testing with everolimus is unlikely to change our conclusion that mTOR inhibition is of limited value in STK11-deficient lung cancer." (PMID 40069402, 2025). "Ongoing clinical trials of several drugs targeting PI3K/AKT/mTOR signaling pathway in lung cancer." (PMID 40041495, 2025). "The modifying Res by substituting a methyl group on the hydroxy group of ring A and introducing a methoxy group at the para position of ring B to create the compound SM-3 results in a more effective targeted suppression of CSCs through the inhibition of the mTOR protein in lung cancer cells." (PMID 40287470, 2025). "This implied that c-kit could regulate the stemness phenotype transformation in gefitinib-resistant lung cancer cells through the AKT/mTOR/4EBP1/eIF4E axis." (PMID 39744423, 2025). "On the basis of these observations, our findings on Ephexin1’s regulation of 5′-TOP mRNA translation, we hypothesized that mTOR target genes, such as HSP90ab1, eEF1a1 and c-Myc, along with Ephexin1, are involved in lung cancer progression." (PMID 40855114, 2025). "Dual inhibition on PI3K and mTOR could not only directly suppress lung caner progression, but also enhance the efficacy of chemotherapy or targeted therapy in lung cancer treatment." (PMID 39953539, 2025). "Besides, preliminary functional data support a model wherein TICRR promotes lung cancer pathogenesis by modulating the PI3K/AKT/mTOR pathway and its downstream network." (PMID 41445727, 2025).